DYNLT2 (dynein light chain Tctex-type 2)
Description:
Component of dynein, a family of motor proteins essential for movement along microtubules. Required for structural and functional integrity of cilia (By similarity). Candidate for involvement in male sterility (By similarity).
Synonyms: TCTE3; TCTEX1D3; TCTEX2; Tctex4; oda12
Tractability: Antibody: UniProt places it where antibodies can reach, with medium confidence.
Gene: Protein-coding gene on chromosome 6 (169,740,106 to 169,751,587, reverse strand). Ensembl gene ENSG00000184786.
Subcellular location: Cytoplasm, cytoskeleton; Cytoplasmic granule; Membrane
Pathways (Reactome):
Organelle biogenesis and maintenance: Intraflagellar transport
Gene Ontology:
Molecular function: protein binding; dynein intermediate chain binding
Biological process: microtubule-based movement
Cellular component: cytoplasm; cytoplasmic dynein complex; membrane; cytoskeleton
Genetic constraint (gnomAD): Loss-of-function variants: 20 observed, 21.12 expected, observed/expected ratio (o/e) 0.95, 90% interval 0.67 to 1.38. The upper end of that interval is the gene's LOEUF score, 1.38, which puts it in group 5 of 6, group 1 being the genes least tolerant of losing a copy. Missense variants: 226 observed, 211.05 expected, observed/expected ratio (o/e) 1.07, 90% interval 0.96 to 1.2. Synonymous variants: 81 observed, 76.8 expected, observed/expected ratio (o/e) 1.05, 90% interval 0.88 to 1.27.
Homologues: Orthologues: chimpanzee DYNLT2 (98% identical), pig DYNLT2 (89% identical), rat Dynlt2 (82% identical), guinea pig DYNLT2 (79% identical), mouse Dynlt2a1 (79% identical), mouse Dynlt2a2 (79% identical), mouse Dynlt2a3 (79% identical), macaque DYNLT2 (76% identical). Paralogues in human: DYNLT4 (22% identical), DYNLT5 (22% identical), DYNLT2B (18% identical), DYNLT3 (13% identical), DYNLT1 (11% identical).
Diseases named in the same sentence as DYNLT2 in open-access papers:
DYNLT2 is named in the same sentence as 2 diseases in open-access papers, as found by Europe PMC text mining. Sharing a sentence is not in itself a finding about the gene and the disease.
DYNLT2 shares sentences with these, for which no sentence is quoted: asthenozoospermia (1 paper); congenital diaphragmatic hernia (1).